ID2 (inhibitor of DNA binding 2)
Diseases named in the same sentence as ID2 in open-access papers (continued):
Sharing a sentence is not in itself a finding about the gene and the disease.
thyroid cancer (1 paper, 2024). "In this study, we have identified for the first time that ID2 is highly expressed in thyroid cancer and is associated with shortened overall survival (OS) and disease-specific survival (DSS) in patients." (PMID 38195969, 2024). "As the role of ID2 varies depending on the cancer type, it is imperative to elucidate how ID2 impacts thyroid cancer progression." (PMID 38195969, 2024). "We have demonstrated that ID2 was involved in promoting thyroid cancer stemness both in vivo and in vitro." (PMID 38195969, 2024). "We found that ID2 significantly promotes thyroid cancer cell proliferation, migration, EMT, and stemness through the PI3K/Akt pathway." (PMID 38195969, 2024). "ID2 was highly expressed in two thyroid cancer cell lines (CAL-62 and K1) compared to normal human thyroid epithelial cells (Nthy-ori 3-1)." (PMID 38195969, 2024). "ID2 holds the potential to serve as a prognostic biomarker and therapeutic target for thyroid cancer patients." (PMID 38195969, 2024). "Analyses using the TCGA and GTEx databases from USCS Xena also showed higher ID2 expression in thyroid cancer versus normal tissues." (PMID 38195969, 2024). "In summary, our results demonstrated that ID2 promotes thyroid cancer cell proliferation, migration and EMT by enhancing Akt activation." (PMID 38195969, 2024). "This study has revealed that overexpression of ID2 promotes proliferation and migration of thyroid cancer cells by upregulating the expression levels of p-Akt." (PMID 38195969, 2024). "In this study, we observed an upregulation of ID2 expression in thyroid carcinoma (THCA) and its correlation with patient survival." (PMID 38195969, 2024). "Besides, in thyroid cancer, higher expression of ID2 was related to shorter overall survival (OS) and disease-specific survival (DSS)." (PMID 38195969, 2024). "This suggested that ID2 can promote the stemness of thyroid cancer cells." (PMID 38195969, 2024). "We investigated the role of ID2 in thyroid cancer metastasis." (PMID 38195969, 2024). "In addition, we examined the mRNA expression relationship between ID2 and ID2-relating molecules in thyroid cancer." (PMID 38195969, 2024). "We further examined the effect of ID2 on thyroid cancer EMT and stemness." (PMID 38195969, 2024). "We speculated that ID2 may regulate the cell cycle molecules in thyroid cancer." (PMID 38195969, 2024). "Taken together, ID2 was upregulated and may serve as a biomarker or target in thyroid cancer." (PMID 38195969, 2024). "ID2 may be a promising therapeutic target for thyroid cancer." (PMID 38195969, 2024). "However, the specific function of ID2 in thyroid cancer remain unclear." (PMID 38195969, 2024). "We hypothesised that ID2 may regulated the activation of PI3K/AKT pathway to promote viability and migration of thyroid cancer." (PMID 38195969, 2024). "However, the relationship between ID2, EMT, and tumor stemness of thyroid cancer remains unclear." (PMID 38195969, 2024).
thyroid tumor (1 paper, 2024). A benign or malignant neoplasm affecting the thyroid gland. "We obtained 28 PTC patients and 16 healthy controls from the GEO database (GSE138198), and found much higher levels of ID2 expression in thyroid tumors than normal controls (p = 0.0022, Fold change = 3.034)." (PMID 38195969, 2024).
tubular adenoma (1 paper, 2023). A usually polypoid neoplasm arising from the glandular epithelium. "GREMLIN1 expression was significantly upregulated, while the inhibitor of DNA binding (ID) proteins ID1, ID2, ID3 and ID4, all major downstream transcription targets of BMP signaling, were found to be significantly downregulated in serrated adenomas compared to tubular adenomas." (PMID 36326956, 2023).
uveal melanoma (1 paper, 2009). A melanoma derived from melanocytes of the uveal tract. "For example, in uveal melanoma Mel202 and Mel290 cells, Id2 suppressed E-cadherin expression through inhibiting the transactivation of its proximal promoter by an unknown regulatory mechanism." (PMID 19257909, 2009).
uveitis (1 paper, 2023). An inflammatory process affecting a part of or the entire uvea. "Therefore, the abnormal Id2/Pim1 pathway in EAU might contribute to Th17 cell differentiation and pathogenicity in uveitis, which could be ameliorated by Id2 inhibition." (PMID 37344856, 2023).
ZIKV infection (1 paper, 2018). "On the opposite end of the spectrum, genes that are underexpressed during DENV infection and overexpressed during ZIKV infection include the transcriptional regulator ID2." (PMID 29451494, 2018).
tumor (118 papers, 2007 to 2025). "LSD1 inhibition (GSK2879552) rescues the Id2-deficient phenotype in tumor models, expanding Slamf6+Tim-3- Texprog cells and enhancing Tcf1 expression in Id2-deficient CD8+ T cells." (PMID 41194917, 2025). "To identify associations between Id2 expression and inferred immune infiltration in human tumors, we investigated the Tumor Immune Single-cell Hub (TISCH) database, a single-cell RNA-seq (scRNA-seq) database focusing on the tumor microenvironment (TME)." (PMID 38287103, 2024). "Among “high-SORL1” clusters, cluster 7 was characterized by the expression of immediate early genes, SPP1, a gene associated with tumor-promoting GAMs, and ID2 involved in pro-tumorigenic polarization of myeloid cells." (PMID 38499808, 2024). "ID2 is a multifunctional transcriptional regulator associated with tumor growth and malignant behavior." (PMID 37497010, 2023). "Numerous biological processes, including cell proliferation, senescence, differentiation, apoptosis, angiogenesis, and tumor transformation, have been linked to the ID2 gene." (PMID 36673815, 2023). "Id2 expression has been linked to tumor initiation, growth, dissemination, and chemotherapy responses." (PMID 35437308, 2022). "Genetic depletion of Id2 in ApcΔ716 mice caused ∼80% reduction in the number of ileal polyps, but had little effect on tumor size." (PMID 26163528, 2015). "Because the loss of Id2 specifically suppresses ileal tumor initiation in ApcΔ716 mice, we confirmed the expression patterns of Id2 and other Id-family members (Id1 and Id3) along the proximal-distal axis of the small intestine." (PMID 26163528, 2015). "To analyze the mechanism of Id2-mediated tumor initiation, we next investigated the effect of Id2-deficiency on the proliferation and apoptosis of normal crypt cells of ApcΔ716 mice." (PMID 26163528, 2015). "Our results on Id-2 expression in ESCC also showed that low level of cytoplasmic Id-2 expression was significantly (P=0.013) associated with poor tumour differentiation." (PMID 18000500, 2007). "In contrast, low-level cytoplasmic Id-2 expression was significantly associated with poorly differentiated tumours (P=0.013)." (PMID 18000500, 2007). "Intriguingly, ID2 showed the least propensity among all signatures, which indicates a diminished predisposition for immunoediting, likely contributing to the observed shorter latency and accelerated tumor proliferation." (PMID 40161734, 2025). "Importantly, the underlying mechanisms controlling Id2 expression during tumor progression are still elusive." (PMID 35437308, 2022). "We found that decreased ID2 expression was associated with reduced tumor cell survival." (PMID 28206987, 2017). "Here, we show that Id2 promotes ileal tumor initiation in Apc-deficient mice." (PMID 26163528, 2015). "The invasion potential induced by Id2 was only partially associated with the down-regulation of the metastasis suppressor E-cadherin, suggesting that multiple molecules associated with tumor metastasis may be implicated in this process." (PMID 19257909, 2009). "Id-2 has been shown to bind and inhibit the function of retinoblastoma protein, a tumour suppressor protein and therefore has been implicated in tumour progression in several cancer types." (PMID 18000500, 2007). "In addition, a statistically significant association was observed between low-level cytoplasmic Id-2 expression and poor differentiation of the tumour (P=0.013)." (PMID 18000500, 2007). "Therefore, in lieu of the potential risk of live albeit attenuated Id2-kd N2a tumor cells we sought to determine whether irradiation of these cells would dampen the effects of this tumor cell vaccine strategy." (PMID 26079374, 2015). "ID2 promotes tumor angiogenesis by functioning as a master regulator of VEGF which activates endothelial cells to proliferate and differentiate." (PMID 40711921, 2025). "Among them, ID1 and ID3, like ID2, are rapidly degraded via the proteasome and function as oncogenes in certain tumor types." (PMID 40607387, 2025).
tumor (continued). "A comparative analysis of ID1, ID2 and ID3 expression further implicated ID1 as the dominant family member during disease progression with a 10‐fold higher expression in the primary tumour that increased further during metastasis." (PMID 40116596, 2025). "Genetic deletion of Id2 impairs CD8+ T cell-mediated immune responses, reduces stem-like CD8+ T cell maintenance, diminishes anti-PD-1 efficacy, and increases tumor susceptibility." (PMID 41194917, 2025). "ID2 and ETS2 genes were found to be expressed by the tumour-associated microglia isolated from human GB tumour biopsies." (PMID 39019900, 2024). "Genetic deletion of Id2 in T cells promotes tumor development by suppressing the immune response and represses the tumor response to PD-1 blockade." (PMID 38287103, 2024). "Genetic deletion of Id2 dampens CD8+ T-cell-mediated immune responses and the maintenance of stem-like CD8+ T-cell subpopulations, suppresses PD-1 blockade and increases tumor susceptibility." (PMID 38287103, 2024). "Deletion of Id2 resulted in a marginally decreased frequency of tumor-infiltrating central memory cells (CD44+CD62L+) among adoptive CD45.2+ OT-I CD8+ T cells from Id2fl/flCd4-Cre+ OT-I mice compared to those from Id2fl/flCd4-Cre− OT-I mice." (PMID 38287103, 2024). "An additional human scRNA-seq dataset originating from 28 GB tumours further confirmed the expression of ID2 and ETS2 genes in tumour-associated microglia/macrophages in the context of GB tumours." (PMID 39019900, 2024). "Taken together, these results suggest that Id2 in T cells prevents tumor development by enhancing the antigen-specific CD8+ T-cell immune response." (PMID 38287103, 2024). "Consistently, in this study, we found that Id2 ablation in CD8+ T cells promoted tumor development by perturbing immune responses, emphasizing the critical role of Id2 in host defense during infection and in cancer." (PMID 38287103, 2024). "Tumour-associated microglia/macrophages were found to express both ID2 and ETS2 genes, hence validating their expression in myeloid cells in the context of GB tumours." (PMID 39019900, 2024). "We found that genetic deletion of Id2 dampens CD8+ T-cell-mediated immune responses, suppresses PD-1 blockade and increases tumor susceptibility in mice." (PMID 38287103, 2024). "Inhibitor of DNA Binding 2 (ID2) plays a crucial role in tumor cell proliferation, invasion, metastasis, and stemness." (PMID 38195969, 2024). "Several of these EPINs have promoters of differentially expressed genes (such as DLL1, STOM and SEC11C in the GEPIA tumor/normal dataset; ID2, RPS27, SEC11C, CASZ1, CRTC2, C5 and STOM in the LNCaP/LHSAR dataset; see Methods, Differential Gene Expression)." (PMID 38057321, 2023). "Cells expressing EYA4 S37E had intact nuclear accumulation of β-catenin and Id2 transcription upon Wnt-3a stimuli, suggesting that Ser37 autophosphorylation restrains the tumor-suppressive phenotypes of EYA4." (PMID 36741265, 2023). "Emerging evidence supports the important role of ID2 in many cancers; however, ID2 expression has distinct effects in different tumor types." (PMID 35729325, 2022). "In particular, the ID2 transcript was significantly downregulated in BC patients with higher pT tumor stages indicating bladder muscle invasion." (PMID 35729325, 2022). "More importantly, AOM/DSS T cells highly expressed Id2 downstream of TGFβ signaling, which has been shown to lead to RORα-dependent tumor-promoting inflammation, evident in this population by high Rora and Il17a expression." (PMID 35600339, 2022). "Simultaneously suppressing CDK1 and boosting ID2 with apigenin strongly repressed tumor growth in a mouse model." (PMID 35729325, 2022). "In contrast, FAM46C and ID2 acted as tumor suppressors in many MM lines as indicated by their positive CSS values, consistent with previous results." (PMID 36115844, 2022).
tumor (continued). "Mechanistically, ID2 acts as a tumor suppressor through PI3K/AKT signaling pathway to inhibit the progression and metastasis of BLCA." (PMID 36313549, 2022). "While Id2 controls tumor progression features, it is still unclear how its established ties to Rb-dependent cell cycle regulation affect tumor cell survival, anchorage independence, and metastasis." (PMID 35437308, 2022). "Using a conditional KO mouse model with ID2 overexpression in DCs, the authors corroborated that STAT3 deficiency and expression of ID2 in DCs enhanced the anti-tumor response." (PMID 35806328, 2022). "As a result, there was a shift in the proportion of effector T cells to Tregs through ID2 expression in DCs, which reversed the poorly immunogenic tumor microenvironment." (PMID 35806328, 2022). "Overexpression of ID2 suppressed the increase in tumor-sphere formation induced by TFCP2L1 overexpression." (PMID 35729325, 2022). "The results revealed that ID2 expression was low expression in tumor tissues and similar results were observed by western blotting." (PMID 34746132, 2021). "Mechanistically, ID2 acts as a tumor suppressor through PI3K/AKT signaling pathway to inhibit the progression and metastasis of BCa." (PMID 34746132, 2021). "We found that ID2 was lowly expressed in BCa tumor tissues, ID2 expression correlated with TNM stage, grade and pathological stage, and that high ID2 expression was positively correlated with OS, DSS, and PFI." (PMID 34746132, 2021). "In this study, we examined the expression of ID proteins (ID1, ID2, ID3, and ID4) in BCa tissues and found that ID2 expression was downregulated and associated with tumor stage and survival." (PMID 34746132, 2021). "The role of ID2 was determined by CCK-8, colony formation, wound healing, transwell and xenograft tumor assays, and the potential mechanism of ID2 in BCa was investigated by RNA sequencing." (PMID 34746132, 2021). "Id2 regulates the Rb proteins, and high levels of Id2 can suppress the Rb tumor suppressor pathway, which blocks progression from G1 to S phase of the cell cycle." (PMID 31882403, 2020). "Paradoxically, ID2 is a tumor suppressor in SV40 large T-driven murine RB, so this model does not mimic human RB in this regard." (PMID 32572160, 2020). "It has been reported that ID2 inhibited cancer invasion and metastasis, and the mRNA expression levels of ID2 were inversely correlated with the tumor metastasis stage in clinical samples." (PMID 32751497, 2020). "By contrast, STAT3 signaling in moDCs inhibited expression of the transcriptional regulator Id2, a pathway that suppressed moDC-mediated anti-tumor activity." (PMID 31947933, 2020). "Paradoxically, forced expression of Id2 in Treg cells enables mice to mount strong anti-tumor immune responses, with reduced melanoma growth and Treg cell numbers in the tumor bed." (PMID 33143070, 2020). "Id2 and Aldh3a1 were consistently upregulated in the independent brain-derived sublines compared with both the primary tumour and lung-derived sublines." (PMID 30642388, 2019). "In the spontaneous metastasis model, expression of Id2 and Aldh3a1 was significantly higher in 4T1 brain-derived sublines compared with sublines from lung metastases or primary tumour." (PMID 30642388, 2019). "Using a model that more faithfully recapitulates the dissemination of tumour cells to secondary sites, combined with in-vivo and in-silico validation studies, we identified ID2 as a promising brain metastasis promoter." (PMID 30642388, 2019). "The expression of EYA4 was obviously increased, while the ID2 expression level was remarkably reduced in tumor tissues of circACVR2A overexpressing group." (PMID 31101108, 2019). "Consistent with our previous results, Id2 overexpressing Treg cells showed higher IL-17A expression in TILs and dLN of Dox-treated tumor bearing mice." (PMID 30413714, 2018).